AZIN1 (antizyme inhibitor 1)
Diseases named in the same sentence as AZIN1 in open-access papers (continued):
Sharing a sentence is not in itself a finding about the gene and the disease.
cancer (56 papers, 2012 to 2025). A tumor composed of atypical neoplastic, often pleomorphic cells that invade other tissues. "The increased rates of RNA-edited AZIN1 in human malignancies are associated with increased tumor angiogenesis, improved cancer cell stemness, and increased cancer cell proliferation." (PMID 40040695, 2025). "Beyond cancer cells, increased expression of AZIN1 through A-to-I editing enhances invasive potential of cancer-associated fibroblasts (CAFs) within the tumor microenvironment in colon, and is an important predictor of tumor invasiveness in CRC." (PMID 39126156, 2025). "In summary, ADAR1 is recurrently associated with tumor-promoting functions across multiple cancer types—via editing of oncogenes (AZIN1, GM2A), suppression of innate immune signaling (PKR/MDA5), and stabilization of key proteins (KYNU)." (PMID 40852728, 2025). "In several of these cancers, AZIN1 has the same editing site and causes similar phenotypic changes in cancer cells." (PMID 35898396, 2022). "The transcript encoding Antizyme Inhibitor 1 (AZIN1) is frequently edited in various cancers, and this editing is associated with enhanced tumor aggressiveness." (PMID 36202978, 2022). "AZIN1, which is physiologically involved in regulating the cell cycle and in stimulating cell proliferation, has been associated with cancer." (PMID 30768610, 2019). "Recent evidence suggests that RNA editing of antizyme inhibitor 1 (AZIN1) RNA is emerging as a key epigenetic alteration underlying cancer pathogenesis." (PMID 30563560, 2018). "AZIN1 is one of the most well-studied ADAR1 substrates in cancer, the edited form of which is strongly associated with cancer progression." (PMID 30585209, 2018). "Recently, some cancer-related RNA editing targets were discovered such as antizyme inhibitor 1 (AZIN1) and glioma-associated oncogene 1 (GLI1)." (PMID 23737728, 2013). "The most common AZIN1 mutations across cancers are missense substitutions." (PMID 38169396, 2024). "Notably, this editing site was recently linked to aggressive cancer phenotypes, analogous to the findings with Azin1 A-to-I editing." (PMID 38954486, 2024). "Moreover, editing events of these genes have been associated with cancer progression (e.g., AZIN1, COPA, CCNI, and FLNB) or neurological disorders (e.g., GRIK2 and GRIA2–4)." (PMID 35406793, 2022). "Indeed, among all editing sites assessed, A-to-I conversion in the single codon corresponding to residue 367 in AZIN1 is associated with clinical features of aggressive cancer subtypes and is particularly interesting." (PMID 36202978, 2022). "Thus, stimulation of cell proliferation in both normal and cancer cells was associated to increased expression of AZIN1." (PMID 30304856, 2018). "In addition, AZIN1 RNA editing has been shown to be a potential prognostic biomarker for overall survival and an independent risk factor for lymph node and distant metastasis in some cancers." (PMID 31847302, 2019). "As a result, the inosine base-pairs with cytosine in a way that mimics guanosine.In CRC, elevated ADAR1 expression increases the RNA editing of AZIN1, and this edited AZIN1 functions as an oncogene by enhancing cancer cell stemness and driving metastasis." (PMID 41361128, 2025). "Patients from each cancer type were then divided into high‐ and low‐expression groups based on the median AZIN1 expression." (PMID 39140420, 2024). "In cancer, antizyme inhibitor 1 (AZIN1) is one of the most studied proteins for A-to-I editing in the coding region." (PMID 38233935, 2024). "Given that AZIN1 participates in polyamine metabolism, AZIN1 has been mostly recognized as a pro‐oncogenic molecule in cancers." (PMID 39140420, 2024). "Recent evidence has strengthened this signature by correlating highly frequent AZIN1 edited site with various cancers occur and pathogenesis to regulate malignant phenotype transformation of cells." (PMID 38169396, 2024).
cancer (continued). "It has been demonstrated that AZIN1 regulates tumor behavior by modulating centrosome duplication and upregulating loricrin to promote differentiation of cancer cells." (PMID 38169396, 2024). "Hyperediting of AZIN1 has turned out to be prognostic factor for survival and metastasis in many cancer types." (PMID 38169396, 2024). "Transcriptome sequencing revealed that A-to-I RNA editing of AZIN1 accounts for high modification rate in various cancers, which is specifically regulated by ADAR1." (PMID 38169396, 2024). "A more specific and effective AZIN1 inhibitor is required, however, for therapeutic intervention in a wide range of cancers." (PMID 38169396, 2024). "Such gain-of-function AZIN1 A-to-I editing has been described in several forms of cancer, contributing to aggressive tumor behavior." (PMID 38954486, 2024). "The upregulation of RNA-edited AZIN1 in human cancers correlates with increased tumor progression and aggressiveness." (PMID 38169396, 2024). "AZIN1 mRNA levels were markedly downregulated in five types of cancer, including GBM, THCA, KICH, KIRC, and KIRP." (PMID 39140420, 2024). "AZIN1 pre-mRNA editing was widely indicated in human diseases, especially human cancers by Transcriptome sequencing directly." (PMID 38169396, 2024). "Recently, studies on RNA editing of AZIN1 have gradually increased and expanded to other cancer types, such as colorectal cancer, esophageal cancer, endometrial cancer, gastric cancer, lung cancer, etc.." (PMID 38233935, 2024). "The protein recoding editing in Azin1 is extensively studied for its role in many cancer types and lately also for its involvement in hematopoietic stem cell differentiation." (PMID 37026479, 2023). "The elevated RNA editing at the S/G site of AZIN1 is most likely a response to type I IFN production from the chronic inflammatory environment of cancers in addition to a possible increase in ADAR1 copy numbers." (PMID 37209819, 2023). "Several RNA editing events show clinically relevant patterns; and importantly, the editing events in AZIN1, COG3, and COPA can functionally drive the growth and migration of cancer cells in a manner similar to driver somatic mutations." (PMID 35365616, 2022). "Supporting this data, ELISA measurements revealed a significant upregulation of IL-8 in CM from cancer cells transfected with edited AZIN1 as compared to the WT AZIN1 group." (PMID 35365616, 2022). "Antizyme inhibitor 1 (AZIN1) is one of the most frequent A-to-I RNA alterations in many human cancers." (PMID 35365616, 2022). "Edited AZIN1 is known to promote cancer cell proliferation and tumor progression through restraining antizyme-mediated degradation of oncoproteins, such as ODC and cyclin D1." (PMID 35365616, 2022). "Based on our results of increased edited AZIN1-induced angiogenesis, we extended the analysis to angiogenic cytokines released from cancer cells overexpressing edited AZIN1 using the Proteome Profiler Human Angiogenesis Array." (PMID 35365616, 2022). "First, we assessed cell migratory phenotypes of HUVEC cultured in CM from cancer cells transfected with the control vector, WT AZIN1, and edited AZIN1, by transwell assays and wound healing assays." (PMID 35365616, 2022). "Prior work has shown that RNA-edited AZIN1 promoted cancer cell proliferation and tumor progression through restraining antizyme-mediated degradation of oncoproteins, such as ODC and cyclin D1." (PMID 35365616, 2022). "In this analysis, the event associated with aggressive tumor subtypes, more advanced stages, and worse survival profiles in the greatest number of cancers was AZIN1 editing." (PMID 36202978, 2022). "Deamination of a single adenosine base in AZIN1 mRNA and the resultant single amino acid change have been independently confirmed to have a remarkable phenotypic impact in multiple cancer types." (PMID 36202978, 2022).
cancer (continued). "This work expands the known role of AZIN1 editing in human cancer and further suggests novel approaches to interfere with edAZIN1-mediated tumor aggressiveness." (PMID 36202978, 2022). "Of special interest are the pre-mRNAs encoding AZIN1, BLCAP, SON and GLI1, all of which display dysregulation in various cancer types." (PMID 34882682, 2021). "While in CRC, the ADAR/AZIN1 systems is involved in back-and-forth communication between cancer cells and fibroblasts." (PMID 33671588, 2021). "A recent pan-cancer study identified an appreciable number of RNA editing sites with potential clinical implications (AZIN1, COG3, and GRIA2)." (PMID 30760294, 2019). "The most well characterised recoding event is the editing of the coding sequence of AZIN1 mRNA in cancers." (PMID 31547885, 2019). "In colorectal cancer, AZIN1 RNA editing exhibits cancer stemness and augments oncogenic potential; while in esophageal squamous cell carcinoma it is associated with aggressive tumour behaviour." (PMID 31547885, 2019). "Conversely, silencing expression of AZIN1 by using RNA interference technology reduced intracellular polyamine levels and decreased the proliferation of cultured cancer cells and prostate tumor growth in vivo." (PMID 30304856, 2018). "To further explore ADAR1-driven RNA editing events, we performed RESSq-PCR analysis on other cancer-associated loci, including the DNA cytidine deaminase APOBEC3D, antizyme inhibitor 1 (AZIN1), and murine double minute 2 E3 ubiquitin protein ligase (MDM2)." (PMID 29203771, 2017). "Together, either IL-6 exposure or continuous lenalidomide treatment enhanced A-to-I editing of GLI1 as well as other cancer-associated associated transcripts, including APOBEC3D, AZIN1, and MDM2." (PMID 29203771, 2017). "In contrast, two of the five cancer types with significantly increased AZIN1 editing showed a significantly decreased expression of ADAR in tumor samples." (PMID 26980570, 2016). "The AZIN1 was an inhibitor for the antizyme and both were highly regulated in human cancers and antizyme induced HIF, during increased cellular redox potential." (PMID 23122428, 2012). "AZIN1 functions as an oncogenic factor that enhances cell proliferation, invasion, and migration capabilities; and cancer stemness characteristics, thereby conferring gain-of-function phenotypes with augmented tumor-initiating potential and aggressive phenotypes." (PMID 39126156, 2025). "AZIN1 is a cell cycle regulator that has been found to be upregulated in a variety of cancers." (PMID 39962590, 2025). "AZIN1 is a cell cycle regulator that is upregulated in a variety of cancers." (PMID 39962590, 2025). "We identified that AZIN1 played a critical role in KIRC among all types of cancers." (PMID 39140420, 2024). "Besides, we review RNA editing, as one of RNA modification types on AZIN1 in human diseases, and A-to-I RNA editing of AZIN1 also has involved in cancer progression." (PMID 38169396, 2024). "Here, our study first reported the anti‐cancer role of AZIN1 in KIRC." (PMID 39140420, 2024). "Next, the prognostic value of AZIN1 was validated in those cancers using GEPIA." (PMID 39140420, 2024). "Then, developing AZIN1 inhibitor for cancer therapy may be superior to targeting polyamine synthetic pathway for the reason that inhibiting intracellular synthesis could lead to polyamine uptake from extracellular fluid by means of compensatory mechanism." (PMID 38169396, 2024). "Additionally, the high frequencies of RNA-edited AZIN1 in human cancers correlates with increase of cancer cell proliferation, enhancement of cancer cell stemness, and promotion of tumor angiogenesis." (PMID 38169396, 2024). "However, knowledge is limited about differences in mechanisms between wild and edited-type AZIN1 in cancers so far." (PMID 38169396, 2024). "Thus, A-to-I RNA editing of AZIN1 contributes to cancer initiation, progression, and therapeutic response." (PMID 38169396, 2024).
cancer (continued). "Furthermore, ADAR1 is overexpressed in fibroblasts from CRC specimens and conditioned medium derived from cancer cells and promotes AZIN1 RNA editing in fibroblasts mediated by ADAR1 expression." (PMID 37958449, 2023). "AZIN1, which is aberrant in different types of cancers, is a major target of ADAR1." (PMID 36747029, 2023). "Additionally, it highlights the importance of RNA editing in general and AZIN1 editing in particular as an underexplored mechanism linking RNA editing to aggressive phenotypes in human cancer." (PMID 36202978, 2022). "However, this new insight into the requirement for edAZIN1 to enter the nucleus to exert its effect provides a rationale for targeting AZIN1 expression, editing or localization as a potential therapeutic approach in multiple cancer types." (PMID 36202978, 2022). "Although AZ is a tumor suppressor and its expression can prevent cell growth and tumorigenesis, AZIN1 competes with ODC to release ODC from the ODC-AZ complex based on the stronger binding ability of AZIN1 and AZ, which is conducive to the polyamine synthesis pathway and promotes cancer progression." (PMID 36119047, 2022). "Furthermore, by resorting to several recent review articles, there were 26 RESs with cancer‐related clinical significance that were covered by our dataset, which resided in 7 genes (AZIN1, BLCAP, COG3, COPA, FLNB, GRIA2, and NEIL1)." (PMID 34319007, 2021). "One of the most frequently edited genes in cancer is antienzyme inhibitor 1 (AZIN1)." (PMID 31847302, 2019). "High levels of AZIN1 RNA editing have been observed in several cancer types." (PMID 31847302, 2019). "Consequently, targeting of AZIN1 through AHR inhibition appears as a promising strategy for cancer therapy." (PMID 30304856, 2018). "According to all these findings, it has been postulated that AZIN1 might be a critical target for cancer therapy." (PMID 30304856, 2018). "determined that RNA-edited AZIN1 plays a significant role in the tumor vascular microenvironment and identifies IL-8 signaling, primarily through the application of small-molecule antagonists, such as reparixin, as a promising therapeutic target in hyper-edited cancer." (PMID 40852728, 2025). "Therefore, identification of suppressing AZIN1 editing may contribute to the development of novel RNA therapeutics and increase success rate of cancer treatment." (PMID 38169396, 2024). "Notably, the differential Azin1 S367G editing in cerebral vessels is conserved between humans and mice, which has been found to enhance cancer cell stemness, promote tumor angiogenesis, and might drive metastasis." (PMID 39156629, 2024). "However, the functional impact of RNA-edited AZIN1 in cancer angiogenesis remains unexplored." (PMID 35365616, 2022). "Interestingly, a series of new findings have established that the RNA editing of AZIN1 may be a potential driver in the pathogenesis of human cancers." (PMID 30304856, 2018). "Further investigations are needed to understand the precise molecular mechanisms which made AZIN1 unique in KIRC, as different from other cancers." (PMID 39140420, 2024). "Although, RNA therapeutics targeting cancer-driven or associated RNA editing events have not yet been identified or introduced into the clinic, AZIN1 may serve as a therapeutic target for anticancer drug development superior to polyamine synthesis inhibitors and warrants further studies." (PMID 38169396, 2024). "We also observed several genes that have been reported to change the editing level in cancer and even drive early tumor invasion and metastasis, including FLNB, SLC22A3, and AZIN1, which had significantly different editing levels in PDAC." (PMID 36895481, 2023). "The RNA codes for the protein Antizyme inhibitor 1 (AZIN1) and is frequently edited in ways that make a variety of cancers more aggressive." (PMID 36202978, 2022). "Conditioned medium from cancer cells led to induction of ADAR1 expression and activation of AZIN1 RNA editing in fibroblasts." (PMID 34616451, 2021).
cancer (continued). "Conditioned medium from cancer cells induced ADAR1 expression and activation of AZIN1 in fibroblasts." (PMID 33671588, 2021). "While only five cancer types showed a significant increase in AZIN1 RNA editing levels with FDR ≤0.05, most cancer types (12 out of 14) showed increased editing with nominal P-value ≤0.05." (PMID 26980570, 2016). "Previous study showed that the non-synonymous RNA-editing sites in AZIN1 (A1099G, ENST00000347770) and DCAF16 (A486G, ENST00000382247) are clinically relevant in cancers." (PMID 27687780, 2016). "The Cancer Genome Atlas (TCGA, TIMER, and GEPIA) were employed for pan‐cancer expression and survival analysis of AZIN1, indicating the unique anti‐tumor role of AZIN1 in KIRC." (PMID 39140420, 2024). "RNA editing level of AZIN1 is higher in many cancer types than that in corresponding non-cancerous tissues." (PMID 38169396, 2024). "For example, AZIN1 and BLCAP promote cancer development after editing." (PMID 37328893, 2023). "AZIN1 and BLCAP have been shown to promote tumorigenesis in various cancers." (PMID 37328893, 2023). "Interestingly, conditioned medium from cancer cells led to both induction of ADAR1 expression and activation of AZIN1 RNA editing in CAFs, resulting in the increased invasive potential of CAFs within the TME in the colon." (PMID 36600243, 2023). "Of these, AZIN1, BLCAP, ITGA2, GLI1, NEIL1, and CDK13 after the editing promote cancer development." (PMID 37328893, 2023). "The binding of AZIN1 inhibits antizyme-1-mediated binding and degradation of the ornithine decarboxylase (ODC) and cyclin D1 (CCND1) oncoproteins, contributing to cancer initiation and progression, and controlling the proliferative and invasive abilities of cells." (PMID 37958449, 2023). "Compared to wild type AZIN1, AZIN1S367G has greater antizyme binding, inhibiting antizyme-mediated degradation of ODC and CCND1, thereby facilitating entry into cell cycle and increasing the malignancy of the cancer cell." (PMID 30585209, 2018). "All the down-regulated genes, in this Panel 3 showed their significant up-regulation in most of many types of cancers (TGM2, CSNK1A1, CTNNA1, NAMPT/Visfatin, TNFRSF1A, ETS1, SRC-1, FN1, APLP2, DMBT1/SAG, AIB1, AZIN1)." (PMID 23122428, 2012). "No statistical significance of AZIN1 expression was observed in other cancer types." (PMID 39140420, 2024). "Notably, emerging data demonstrating influence of AZIN1 on cancer stemness and microenvironment indicate that anticancer strategy should not be limited to direct manipulation of AZIN1 in cancer cells." (PMID 38169396, 2024). "For those cancers lacking normal tissues in the TIMER dataset, we employed the GEPIA database to illustrate the AZIN1 gene expression." (PMID 39140420, 2024). "Nevertheless, we observed a significant correlation between ADAR1, but not ADAR2, mRNA, and protein expression and editing of AZIN1, a target of both ADAR1 and ADAR2 and one of the eight recoding sites recently described to increase in cancer, in the collection of cell lines." (PMID 36221913, 2022). "However, in this cluster, the AZIN1 and TICAM2 were down-regulated and were lacking direct experimental evidence to support their regulation with HIF or hypoxia during cancer." (PMID 23122428, 2012).